GLP1R (glucagon like peptide 1 receptor)
Diseases named in the same sentence as GLP1R in open-access papers (continued):
Sharing a sentence is not in itself a finding about the gene and the disease.
Obesity (continued). "Semaglutide, a glucagon-like peptide-1 receptor agonist, is an antidiabetic medication that has recently been approved for the treatment of obesity as well." (PMID 37239841, 2023). "In rodents, diet-induced obesity or the availability of palatable food reduces the anorectic effect of GLP1R activation by peripheral EX4 administration." (PMID 37293487, 2023). "Several animal experiments and clinical trials have demonstrated that GLP-1R agonists are more effective in treating or preventing obesity." (PMID 36843578, 2023). "Younger patients experience a greater reduction in EAT with pharmacologic obesity therapy with glucagon-like peptide 1 receptor antagonists (GLP-1 RAs) and SGLT2is." (PMID 37176781, 2023). "This is an area of research that is likely to continue to develop as Novo-Nordisk recently announced that its amylin receptor and GLP-1R dual-agonist, Amycretin, is set to enter phase 1 clinical trials in individuals living with obesity." (PMID 36943057, 2023). "Butyricimonas virosa had a beneficial effect on metabolic disorders, including obesity and hyperglycemia, via GLP-1R in the liver in a mouse model of obesity." (PMID 35655996, 2022). "It must be noted that glucagon-like peptide-1 receptor (GLP-1R) agonists, approved to treat obesity, elicit robust improvements in overweight, and provide cardioprotection in individuals at risk of or with pre-existing cardiovascular disease." (PMID 35885941, 2022). "This response to liraglutide mirrors other real‐world studies, but of note, the dose was lower than that currently advocated for obesity, and newer formulations of GLP‐1R agonists are likely to be even more potent." (PMID 35338558, 2022). "Some GLP-1R agonists, like Liraglutide (taken once daily) or Dulaglutide (taken once weekly), are already licensed for T2D and obesity management in humans due to their ability to mimic the effects of GLP-116–18." (PMID 35140289, 2022). "It emphasizes how structural refinements and biochemical modifications can extend the application of GLP-1R agonists from the treatment of T2D to obesity." (PMID 35299971, 2022). "BI 456906 is a potent GCGR/GLP-1R dual agonist with robust anti-obesity efficacy achieved by increasing energy expenditure and decreasing food intake." (PMID 36356832, 2022). "Novel therapeutic approaches for T2DM and obesity treatment rely on the incretin effect of GLP-1R agonists on both pancreatic β-cells and other peripheral and central mechanisms of action." (PMID 35408810, 2022). "GLP1R (Glucagon-Like Peptide 1 Receptor; HGNC:4324) is one of the genes associated with obesity and T2D risk identified by GWAS." (PMID 36339410, 2022). "Is there any role of the novel anti-obesity agents (e.g. glucagon-like peptide-1 receptor agonists) in PD patients?" (PMID 37675033, 2022). "Of appreciable note, in contrast to a vast majority of previously employed anti-obesity medications, GLP-1R agonism improves cardiovascular (CV) health in patients with T2D." (PMID 35299971, 2022). "A variety of structurally and chemically refined GLP-1R analogs have received extensive attention and have been implemented in clinical use for the treatment of T2D and obesity." (PMID 35299971, 2022). "Liraglutide, a glucagon-like peptide-1 (GLP-1) analog that binds to and activates GLP-1R, is primarily used to treat type 2 diabetes and obesity." (PMID 35450076, 2022). "The recent availability of once-weekly subcutaneous 2.4 mg semaglutide (a glucagon-like peptide-1 receptor agonist; WegovyTM Novo Nordisk A/S, Bagsværd, Denmark) has changed the scene, and semaglutide is considered a ‘game changer’ in the treatment of obesity." (PMID 35949360, 2022). "MS-275 improved the glycemic control and reduced obesity in diet-induced obese mice by augmenting the glucagon-like peptide-1 receptor in pancreatic beta cells." (PMID 36077368, 2022). "GLP-1R agonists are now widely used therapeutics to treat type 2 diabetes and more recently obesity." (PMID 36309763, 2022).
Obesity (continued). "Glucagon-like peptide 1 receptor agonists (GLP-1RAs) are a class of medications used in the pharmacotherapy of obesity and T2D." (PMID 36339410, 2022). "Some of the most recent drug developments for T2DM and obesity are the triagonists for GLP-1R, GIPR, and GCGR (GLP-1R/GIPR/GCGR)." (PMID 36145148, 2022). "In the US, there are now two GLP-1R agonists (Liraglutide and Semaglutide) approved for use in the treatment of obesity." (PMID 35328759, 2022). "Dipeptidyl peptidase-4 (DPP-4) inhibitors which increases GLP-1 and gastric inhibitory polypeptide (GIP) incretin hormone concentrations and GLP-1 receptor (GLP-1R) agonists are now widely used to treat type 2 diabetes and obesity." (PMID 36296337, 2022). "At the end of 2014, liraglutide 3 mg became the first GLP1R agonist to be approved for the treatment of obesity, at approximately twice the highest dose employed in the treatment of T2D." (PMID 34815532, 2022). "In animal models of obesity, administration of dual GLP‐1R/GCGR agonists resulted in superior weight loss, lower glucose levels, and reduced food intake compared with pure GLP‐1R agonists alone." (PMID 34713962, 2022). "Recently, glucagon like peptide-1 receptor agonists (GLP-1 RA) has been identified as the most promising intervention in treating obesity." (PMID 36654602, 2022). "Delineating the relative contribution of GcgR agonism to the efficacy of triple GLP-1R/GIPR/GcgR agonists remains a critical question in the field of obesity pharmacology." (PMID 35809773, 2022). "It is also worth noticing that the most prominent anti-obesity effect of GIPR agonists as well as antagonist is accomplished in combination with GLP-1R agonists indicating an important interplay between the two incretin hormones and their receptors." (PMID 34760890, 2021). "According to our earlier data, a special role in the disturbance of carbohydrate metabolism in obesity is played by the occurrence of polymorphisms in the GIPR and GLP-1R genes." (PMID 33959145, 2021). "Another strategy to treat diabetes and obesity with dual active peptides is exploiting the agonism toward incretin receptors GLP-1R and GIPR." (PMID 34195230, 2021). "Recently the FDA approved the use of semaglutide (a new generation GLP-1R agonist) for the treatment of obesity." (PMID 35002645, 2021). "This reduces obesity and improves dyslipidaemia and hyperglycaemia more so than sole activation of either GLP-1R or ER." (PMID 34093449, 2021). "Nevertheless, preclinical studies demonstrated the anti-obesity effect of OXM since a chronic administration leads to superior weight loss and comparable glucose lowering to a GLP1R-selective peptide." (PMID 34680059, 2021). "Given the successful application of liraglutide in this regard and the scale of the obesity problem, other GLP-1R mimetics are beginning to be touted as treatment options for obesity." (PMID 34093449, 2021). "We evaluated the expression of essential metabolic and immune sensor genes, such as isotypes of PPAR and GLP-1R in leukocytes, and their correlation with metabolic, immune, and anthropometric factors in a Colombian’s pediatric population with obesity." (PMID 33292260, 2020). "Initially, GLP-1R agonists were thought to be limited to T2D treatment, but it has become clear that these drugs have the potential to treat other diseases such as obesity, CVD, dementia and NAFLD2,7,12,77,103." (PMID 32269764, 2020). "The consequences of obesity on the development of IR and activation of a chronic inflammatory response allowed to establish a relationship between GLP-1R and PPARs." (PMID 33292260, 2020). "Co-agonism of GLP-1R and glucagon receptor (GR) was also shown to reduce body weight synergistically in rodent obesity models." (PMID 32269764, 2020).
Obesity (continued). "Our findings show that MS-275 enhances the expression of the genes involved in the GLP-1R signaling cascade improving fasting glycemia upon a short-term treatment and a chronic combined therapy reduces obesity in the DIO rodent model." (PMID 33349332, 2020). "This protocol can be used to prepare large quantity of the target GLP-1R agonist with high purity for clinical testing and subsequent commercialization as a therapeutic for T2D and obesity." (PMID 32481528, 2020). "Liraglutide is a glucagon-like peptide-1 receptor (GLP-1R) agonist that is used to treat T2D and obesity." (PMID 33193093, 2020). "Given that both T2D and obesity represent important risk factors for cardiovascular disease (CVD), there is emerging interest to establish the potential cardiovascular benefits of GLP-1R stimulation." (PMID 30532733, 2018). "Previous candidate gene studies on obesity and its related traits have reported GLP1R in European Americans, TRHR in Mexican-Mestizos and MMP1 in Koreans." (PMID 29868124, 2018). "For instance, the GLP-1R agonist exendin-4 decreased hepatic steatosis and inflammation in mice with obesity or atherosclerosis." (PMID 30405191, 2018). "The anti-inflammatory and antioxidant effects of GLP-1R agonist on kidney injury are well-known, but its direct effect on renal metabolism in obesity has rarely reported." (PMID 29590132, 2018). "GLP-1R agonists have previously been shown to either prevent or ameliorate experimental obesity and preserve insulin sensitivity in multiple preclinical models." (PMID 30459598, 2018). "Glucagon-like peptide-1 receptor (GLP-1R) agonists are effective anti-obesity drugs but their use is limited by side effects." (PMID 29317623, 2018). "Altogether, it is likely that GLP-1R signalling and subsequent sympathetic outflow differ during obesity and lean conditions." (PMID 26254578, 2015). "We show that combination therapy of the MC4R agonist RM-493, which has shown to be highly selective and safe in terms of its cardiovascular profile, with the GLP-1R agonist liraglutide potently reverses diet-induced obesity and improves glucose metabolism." (PMID 25652173, 2015). "Although several line of evidence suggests that GLP-1 plays some roles in resistance to diet-induced obesity, Glp1r-/- mice exhibited resistance to diet-induced obesity due to enhanced physical activity and increased energy expenditure." (PMID 26378455, 2015). "In this paper we show that the GLP-1R agonist liraglutide delays progression towards obesity and prandial hyperglycemia and efficiently enhances in vivo GSIS in a mouse model of GC-induced metabolic syndrome." (PMID 24423471, 2014). "The emergence of glucagon‐like‐peptide‐1 receptor agonists (GLP‐1RAs) and dual glucose‐dependent insulinotropic polypeptide (GIP)/GLP‐1 receptor agonists has fundamentally transformed obesity management, offering highly efficacious pharmacological approaches to weight loss." (PMID 41145379, 2026). "Moreover, the potential cancer-preventive effects of newer obesity treatments, including glucagon-like peptide-1 receptor agonists, remains to be determined." (PMID 41490246, 2026). "With the approval of glucagon-like peptide-1 receptor agonists (GLP-1 RAs) for pediatric obesity, families are increasingly considering pharmaceutical treatment alongside lifestyle optimization for their children, although how caregivers will make these decisions remains unexplored." (PMID 41499114, 2026). "While glucagon-like peptide-1 receptor modulators (GLP-1 RMs) are established therapies for obesity, their role in the management of dumping syndrome remains unclear." (PMID 41854998, 2026). "Incretin-based obesity treatments-glucagon-like peptide-1 receptor agonists (GLP-1 RAs) and dual glucagon-like peptide-1 receptor/glucose-dependent insulinotropic polypeptide receptor agonists (GIP/GLP-1 RAs or dual agonists)-are a major stride in the evolution of obesity management." (PMID 41598480, 2026).
Obesity (continued). "However, it is worth highlighting that chronic antagonism or knockout of GLP1R produces similar protection against diet-induced obesity in mice, implying that both incretin hormones exhibit paradoxical agonist/antagonist effects." (PMID 40166681, 2025). "Another incentive for this study was to test the notion emerging from a few previously published studies that GPR61 has a role in metabolic regulation and if so, postulate that it can be grouped with other GPCRs with established links to obesity (eg. glucagon-like peptide-1 receptor)." (PMID 40133016, 2025). "The GLP-1R is an effective pharmacologic target for treating obesity." (PMID 40157531, 2025). "The alteration of certain obesity-promoting genes (e.g., FTO and peroxisome proliferator-activated receptor gamma gene (PPARγ)) and anti-obesity genes (e.g., LEP, GLP-1R, and POMC) may be associated with obesity." (PMID 40868241, 2025). "Recently, clinical trials of tirzepatide, a dual GLP-1R and glucose-dependent insulinotropic polypeptide receptor (GIPR) agonist, have achieved approximately 20% weight loss in substantial proportions of people with obesity." (PMID 41178710, 2025). "Overall, evidence suggests the potential for GLP-1R agonists to lower the risk for gastrointestinal cancers, even in the absence of obesity." (PMID 41178720, 2025). "Thus, all current evidence points to the suppression of energy intake being the underlying mechanism responsible for the beneficial effects of GLP-1R agonists on body weight in patients with obesity and/or T2D." (PMID 39963285, 2025). "But caution is warranted when interpreting these data, since protection from diet-induced obesity was also initially reported with genetic or pharmacological inhibition of the GLP-1R, which subsequently was demonstrated to be an excellent drug target for weight loss." (PMID 40024571, 2025). "This alarming epidemiological trend has prompted a more proactive approach to obesity management, including a marked increase in prescriptions for anti-obesity medications (AOMs), such as glucagon-like peptide-1 receptor agonists (GLP-1 RAs; including semaglutide)." (PMID 41010291, 2025). "Hence, pharmaceutical companies have developed different GLP-1R agonists (GLP-1RAs) to target obesity and T2DM, which comprised multibillion-dollar businesses." (PMID 40592472, 2025). "Therefore, while GLP1R-based medications such as Semaglutide and Tirzepatide have revolutionized obesity treatment, there is still a significant unmet need to maximize long-term and sustainable weight loss." (PMID 40961927, 2025). "Moreover, a recent case report highlighted increased BAT activity in a woman with obesity treated with the GLP-1R agonist semaglutide." (PMID 40892365, 2025). "Anti-obesity treatment by the GLP-1R agonist semaglutide activates satiety pathways." (PMID 40146831, 2025). "However, since the approval of GLP-1R analogs for the treatment of obesity, surprisingly few studies have been done to understand ingestive behavior." (PMID 38454010, 2025). "As a result, GLP-1R agonists are considered promising candidates for obesity treatment." (PMID 41150735, 2025). "Alternatively, the monomeric compound, tirzepatide (ZepboundTM), targets both GLP-1R and glucose-dependent insulinotropic polypeptide receptor (GIPR), and was recently reported to elicit 20.9% and 25.3% weight loss in humans with obesity over 72- and 88-week trials." (PMID 39502365, 2025). "Moreover, preclinical and clinical studies have shown that brown adipose tissue (BAT) is a new potential target for GLP‐1R agonists in the treatment of obesity." (PMID 40742315, 2025). "The therapeutic potential of GIPR:GLP-1R co-agonism extends beyond managing T2D and obesity." (PMID 40024571, 2025). "These diverse functions make GLP-1R a key therapeutic target for managing diabetes and obesity." (PMID 40001594, 2025).
Obesity (continued). "Recent data on individuals living with overweight and obesity treated with the GLP-1R/GCGR co-agonist SAR425899 indicated that such individuals exhibit a smaller-than-expected decrease in the sleeping metabolic rate, increased fat oxidation but no overt induction of energy expenditure." (PMID 40892365, 2025). "Glucagon-like peptide-1 receptor agonists and lifestyle interventions effectively treat overt obesity, but the benefits/risks of their combined early intervention during middle age remain unclear." (PMID 41462691, 2025). "By contrast, other studies have shown that global GIPR-KO mice are protected from both obesity and insulin resistance when fed a high-fat diet, and GIPR antagonism coupled with GLP-1R agonism leads to weight loss in early clinical trials and mouse models, possibly by preventing leptin resistance." (PMID 40857106, 2025). "Recent advances highlight innovative strategies, including hypoglossal nerve stimulation (HGNS), anti-obesity pharmacotherapy with glucagon-like peptide-1 receptor agonists, and upper airway muscle–targeted agents, which exemplify precision medicine approaches tailored to individual OSA phenotypes." (PMID 41226983, 2025). "Emerging evidence suggests that semaglutide, a glucagon-like peptide-1 receptor agonist (GLP-1 RA), may offer a more comprehensive therapeutic approach for male infertility associated with diabetes and obesity." (PMID 40927290, 2025). "As opposed to singular incretin effects, oxyntomodulin (OXM) activates glucagon receptors (GCGR) and glucagon‐like peptide‐1 receptors (GLP1R), demonstrating a more dynamic range of effects that are more likely to align with evolving ‘health gains’ goals in obesity care." (PMID 39495024, 2025). "Firstly, GLP-1R agonists reduced body weight and obesity in PCOS." (PMID 39858999, 2024). "Future research directions for the use of GLP-1R agonists in the treatment of pain and headache disorders should focus on conducting human trials to evaluate their efficacy and safety, particularly in individuals with comorbid obesity." (PMID 38997662, 2024). "However, activated XBP1s and ATF6 were insufficient to increase GLP-1R’s use of Gs signaling under Tm- or obesity-induced ER stress conditions." (PMID 38376482, 2024). "Promising findings of glucagon-like peptide-1 receptor agonists, such as semaglutide and beinaglutide, have spurred many individuals living with obesity to adopt new pharmacotherapies, leading this group to increasingly access OMC to get prescriptions for weight-loss drugs." (PMID 39602197, 2024). "However, recent studies have expanded the understanding of GLP-1R agonists beyond their anti-diabetic and anti-obesity effects." (PMID 39858999, 2024). "Before the creation of DIAs, the most effective non-surgical treatments for obesity were GLP-1 receptor (GLP-1R) monoagonists such as semaglutide, which cause an average weight reduction of about 15 %." (PMID 39612941, 2024). "Furthermore, a new clinical trial is underway to determine if the GLP-1R signaling pathway influences airway inflammation in obese asthmatics, known as the GLP-1R Agonist in the Treatment of Adult, Obesity-related, Symptomatic Asthma (GATA-3) study." (PMID 40474934, 2024). "GLP1R agonists are increasingly used to treat obesity and have been proposed for treating asthma." (PMID 39200943, 2024). "Consequently, there has been growing interest in evaluating GLP-1 receptor (GLP-1R) agonists for the prevention or treatment of cancers, particularly those associated with obesity." (PMID 39931650, 2024). "With the growing demand for obesity OMC, especially due to the emergence of new pharmacotherapies, such as glucagon-like peptide-1 receptor agonists, individuals living with obesity are seeking both advice on obesity management and the prescription of obesity drugs." (PMID 39602197, 2024).